RN7SL20P (RNA, 7SL, cytoplasmic 20, pseudogene)
Gene: Miscellaneous RNA gene on chromosome 22 (31,757,202 to 31,757,498, forward strand). Ensembl gene ENSG00000242251.
Homologues: Orthologues: chimpanzee Metazoa_SRP (99% identical), macaque Metazoa_SRP (91% identical), dog Metazoa_SRP (56% identical). Paralogues in human: RN7SL1 (82% identical), RN7SL2 (82% identical), RN7SL3 (81% identical), RN7SL464P (81% identical), RN7SL655P (81% identical), RN7SL122P (81% identical), RN7SL220P (80% identical), RN7SL145P (80% identical), RN7SL14P (80% identical), RN7SL778P (80% identical), RN7SL147P (79% identical), RN7SL543P (79% identical), and 704 more.